RAD51 (RAD51 recombinase)
Diseases named in the same sentence as RAD51 in open-access papers (continued):
Sharing a sentence is not in itself a finding about the gene and the disease.
tumor (continued). "Mechanistically, selinexor reduces Myc binding to the RAD51 and CHEK1 promoters, thereby decreasing the expression of DNA repair proteins and sensitizing tumor cells to platinum-induced DNA damage." (PMID 41440011, 2025). "Knocking out RAD51 can effectively kill tumor cells by crippling their ability to repair DNA62, 63, thus suppressing tumor growth." (PMID 39744578, 2025). "Intersection of these gene sets yielded four high-confidence tumor dependency genes (TONSL, TIMELESS, RFC3, RAD51) for further investigation." (PMID 41179682, 2025). "RAD51 and BRCA2, in particular, show promise for predicting tumor aggressiveness and patient outcomes, as well as response to therapy." (PMID 40869030, 2025). "Tumor sections from CBPt-treated animals also presented with higher levels of HRR-related proteins, including RAD51 and BRCA1, whereas this increase was reduced in the AQB + CBPt group." (PMID 41353219, 2025). "Recent efforts have used tumor immune dysfunction and exclusion (TIDE), a mRNA expression-based algorithm, linking RAD51 expression to potential immunotherapeutic responses." (PMID 38607586, 2024). "Functional assays demonstrated that two miRNAs acted as tumor-suppressive miRNAs in BC cells by targeting cell-cycle-related genes (e.g., TRIP13, CCNB1, RAD51, PSPH, CENPN, KPNA2, and MXRA5)." (PMID 39728605, 2024). "Previous studies have shown that emodin reduces the mRNA and protein stability of RAD51 in NSCLC, influencing genes related to apoptosis, tumor metastasis, and chemotherapy resistance, ultimately leading to cell apoptosis." (PMID 39629137, 2024). "RAD51 paralogs, including RAD51B, RAD51C, RAD51D, XRCC2 and XRCC3, have emerged as essential tumour suppressors, forming two subcomplexes, BCDX2 and CX3." (PMID 39268578, 2024). "By contrast, the profound RAD51 recruitment defects that characterized human BARD1∆/∆ HCT-116 cells and murine KB1P tumor cells were only slightly ameliorated in shieldin-inactivated derivative cell lines." (PMID 39227718, 2024). "For in vitro and in vivo tumor models, combination trastuzumab and cetuximab pre-treatment increased DNA damage (increased phospho-γ H2AX and decreased Rad51) and decreased tumor hypoxia." (PMID 38355949, 2024). "Upon review of the RAD51 paralogs, both RAD51B (7th percentile) and RAD51D (6th percentile) showed low RNA expression in the tumor compared to the TCGA STAD dataset." (PMID 36964191, 2023). "Here we have described the structural basis for binding of the BRCA2 C-terminus to the RAD51 nucleoprotein filament, a critical interaction for maintenance of genomic integrity by the BRCA2 tumour suppressor protein." (PMID 37919288, 2023). "As observed in T302 tumours, ORC1C1721T/C1721T cells still showed RAD51 focus formation after cisplatin treatment." (PMID 37029129, 2023). "In contrast to the RAD51-FFPE test, tumor tissue is irradiated with 5 Gy ionizing radiation to induce DNA damage prior to fixation." (PMID 37725154, 2023). "A statistically significantly lower percentage of RAD51+/GMN+ and BRCA1+/GMN+ tumor cells were observed in VLS than in VSS; a similar percentage of γH2AX+/GMN+ cells were found in both patient subgroups." (PMID 37686585, 2023). "RAD51 scores (i.e., the percentage of RAD51+/GMN+ cells) are used as a functional HR read-out in tumor samples, where low RAD51 scores indicate HRD." (PMID 37725154, 2023). "As we had access to cryopreserved tumor tissue from the 63 BC samples in our cohort with informative RAD51-FFPE scores, we determined RECAP scores on matched tumor samples." (PMID 37725154, 2023). "We quantified RAD51, a key HR protein, in immunostained formalin-fixed, paraffin-embedded (FFPE) tumor samples obtained from chemotherapy-naïve and neoadjuvant chemotherapy (NACT)-treated HGSC patients." (PMID 36805632, 2023).
tumor (continued). "Related studies have shown that the DNA damage repair mechanism in tumor cells is extremely active, and a series of DNA damage repair-related proteins (ATM, DNA-PKcs, and Rad51) are involved in the regulation of tumor radiation resistance." (PMID 36908704, 2023). "In RAD51-based functional HRD tests, the ability of tumor cells to accumulate RAD51 protein at sites of DNA damage in proliferating (geminin-positive, GMN+) tumor cells is assessed." (PMID 37725154, 2023). "We also performed Rad51 foci formation assays on KPC and KPC-Brca2–/– tumor cells, both untreated or in response to 10 Gy ionizing radiation (IR)." (PMID 36976649, 2023). "We, thus, evaluated the percentage of RAD51 foci/geminin-positive (RAD51+/GMN+) cells and BRCA1 foci/geminin-positive (BRCA1+/GMN+) cells in the FFPE tumor samples of the same patients." (PMID 37686585, 2023). "miR-125a, a tumor suppressor, can attenuate the malignant behaviors of CSCC cells by targeting Rad51." (PMID 35332852, 2022). "Immunohistochemical analysis of tumor xenografts showed that dinaciclib potently lowered the expression of CD44 and Rad51 in SAM68 down-regulated cells." (PMID 35217791, 2022). "In this regard, the main targeting components of DNA repair machinery such as RAD51, XRCC3, RPA‐1 in HR and XRCC4, KU70, KU80 in NHEJ can open a new window for treatment of the EC by sensitizing tumor cells to radiotherapy." (PMID 36147024, 2022). "The superimposed deduction of BRCA1, RAD51 and PARP1 with both sc-13 and NU-7441 treatment indicated the two essential pathways critical for tumor cell replication and genome stability in response to replication stress." (PMID 35414100, 2022). "The results showed that, radiological DNA damage and repair related proteins (KU70 and RAD51) for the 131I-EM@ALA group were overexpressed both in liver and tumor cells." (PMID 35477389, 2022). "Considering our previous data indicating that decreased RAD51 expression is correlated with decreased proliferation of Sus\fP2 cells after exposure to up to 10 Gγ, the role of NHEJ in tumor-cell survival seems insignificant." (PMID 35992802, 2022). "(C) Immunohistochemistry analysis of the expression of EGF and RAD51 in control and METTL3-KD tumor tissues." (PMID 35502895, 2022). "SMAD4, Rad51 and CHK1 expression was assessed in HPV-positive and HPV-negative HNC using TCGA data, a panel of 14 HNC cell lines and 8 fresh tumour tissue samples from HNC patients." (PMID 35144669, 2022). "In our cohort, a comprehensive tumor profile including homologous recombination genes (i.e., ATM, PALB2, RAD50, RAD51, RAD51B, RAD51C, RAD51D...) was performed for 100 cases, finding pathogenic alterations in four tumor samples, as previously reported." (PMID 35406410, 2022). "RAD51 is closely related to HRD and drug sensitivity to PARP inhibitors, reflecting the HR status of tumor cells." (PMID 35626017, 2022). "The dual inhibition of RAD51 and PARP sensitized tumor cells with wild type PTEN, confirming this as a targeted strategy." (PMID 34746010, 2021). "We report here the discovery of CAM833, a sub-micromolar chemical inhibitor of the regulatory protein-protein interaction between the RAD51 recombinase and the BRC repeat motifs of the tumor suppressor BRCA2." (PMID 33662256, 2021). "We only found 5 DEGs (BIRP1, PARP1, RFC4, RMI2, and RAD51) had protein expression data in HPA and the results showed that the expression levels of BIRP1, PARP1, RFC4, RMI2, and RAD51 in BRCA tumor tissues were higher than in normal tissues." (PMID 34408776, 2021). "FOXM1 inhibition was therefore shown to counteract this tumor adaption of increased HR and to downregulate BRCA1/2 and RAD51." (PMID 33668819, 2021). "Our findings uncovered RFWD3-dependent Rad51 ubiquitination was the novel mechanism of VPA-mediated radio-bidirectional effect, VPA is a potential adjuvant treatment for tumor RT." (PMID 33842359, 2021).
tumor (continued). "Secondly, the threshold for functional HRD was calibrated by performing a side-by-side comparison of RAD51-FFPE and previously published RECAP data of matching EC and OC tumor specimens." (PMID 34203855, 2021). "These drugs are tumor-specific radiosensitizers that suppress both NHEJ and HR by downregulating RAD51, RAD51 foci, and DNA-PKcs Ser2056/Thr2609 phosphorylation." (PMID 34337349, 2021). "Then, in the tumor microenvironment, we utilized the CIBERSORT database to investigate the disparities among the Rad51 high expression group and low expression group." (PMID 34115569, 2021). "IHC and Western blotting in tumor tissues showed that expression levels of γ-H2AX, p-ATR, RPA32, CHK1, and RAD51 were upregulated, and the phosphorylation level of CHK1 (p-chk1) was downregulated." (PMID 34660289, 2021). "In agreement, the results of Western blotting in tumor tissues showed that expression levels of γ-H2AX, p-ATR, RPA32, CHK1, and RAD51 were upregulated, and the phosphorylation level of CHK1 (p-chk1) was downregulated." (PMID 34660289, 2021). "In the SG-resistant, BRCA1/2-wildtype MDA-MB-231 TNBC tumor line, several HRR proteins were found to be upregulated upon SG exposure, among them ERCC1 and Rad51." (PMID 33196706, 2020). "The average ΔCt values of RAD51 mRNA expression in CRC tissue was 3.72 ± 2.7, and those observed in paired adjacent non-tumor tissues was 5.5 ± 2.34." (PMID 31973027, 2020). "Tumor induction of nuclear biomarkers of DNA damage response (DDR) γH2AX, pNBs1, and Rad51 was assessed in the context of MGMT and MMR protein expression for expansion cohort patients." (PMID 33216844, 2020). "Five HR cofactors – the RAD51 paralogs RAD51B, RAD51C, RAD51D, XRCC2 and XRCC3 – recently emerged as crucial tumor suppressors." (PMID 32669601, 2020). "In the current study, we found that the five differential expression genes (NFBD1, BRCA1, BRCA2, RPA1 and RAD51) were involved in NPC radioresistance, which was further validated in CNE2-RR cells, tumor xenografs and NPC patients." (PMID 32015678, 2020). "We found that inhibition of AKT-signaling in GIST and STS cell lines results in a significantly decreased expression of Rad51 recombinase and number of residual Rad51/BRCA1 foci in Dox-treated tumor cells." (PMID 33266502, 2020). "The importance of this domain in the overall function of gene, as a tumor suppressor, is due to the binding of BRCA2 protein with Rad51 and their role in homologous recombination process." (PMID 32438681, 2020). "When we depleted CHD4, there was decreased RAD51 protein and mRNA in GBM cell lines and tumour initiating cells." (PMID 30872624, 2019). "Compared to the expression levels in normal tissue, other genes, such as ADRB3, BTG2, DUSP4, RAD51 or FBLX7, were downregulated in specific tumor types, and ANG, ESD and STL7 were downregulated in most tumor types." (PMID 31159852, 2019). "Furthermore, a frequency distribution subdivision based on clinical parameters available for 34 tumors revealed that the reaction of RAD51-foci upon hyperthermia was not dependent on tumor grade, stage, recurrence or European Association of Urology risk stratification." (PMID 30550547, 2018). "With regards to their functions, CHEK1, RAD51 and CDC25A have been suggested to promote tumor development, while GADD45A can act as a tumor suppressor." (PMID 30042885, 2018). "Our data define two functions for the tumor suppressor and HR mediator protein, BRCA2, in RAD51 filament assembly." (PMID 29309696, 2018). "This supports the function of P38 as a tumour suppressor, and the mechanism is substantiated by the link between p-P38 and DNA repair markers including nuclear BRCA1 and RAD51 in the current study." (PMID 30352570, 2018). "For the mice injected with BRCA1-mutant SUM149 cells, RAD51 KD and PARP inhibition significantly inhibited tumor growth in the early stage." (PMID 28359295, 2017).
tumor (continued). "RAD51 expression proved to be an independent prognostic factor (p=0.038) for DFS, as did tumor stage and pathological response (p=0.04 and p=0.003, respectively)." (PMID 29212225, 2017). "In human tumors, expression of the repair proteins RAD51, KU70 and RIF1 was strongly suppressed in hypoxic peri-necrotic tumor areas." (PMID 29156796, 2017). "Moreover, ionizing radiation (IR)-induced RAD51 foci assemble in olaparib-resistant Brca1−/−, 53BP1-deficient cells (albeit not at the same level as in Brca1+/+ cells), but not in olaparib-sensitive Brca1−/− tumor-derived cells." (PMID 26748828, 2016). "Therefore, the detection of RAD51 foci by IHC and IF, in ex vivo samples or in tumor biopsies during neoadjuvant therapy, may be predictive of HR defects and sensitivity to PARPi, given that PARP inhibition or loss results in an increasing RAD51 foci formation in HR intact cells." (PMID 27884198, 2016). "The tumor suppressor BRCA1 plays a key role in HR by promoting end resection, which enables loading of the RAD51 recombinase and initiation of HR-mediated repair." (PMID 26748828, 2016). "Next, we examined tumor biopsies from patients (n = 29) using immunohistochemistry to investigate the patterns and intensities of LIN28, OLIG2, and Rad51 expression." (PMID 27074032, 2016). "In human tumor cells such as MCF7, RAD51 forms higher levels of spontaneous foci that most often appear as simple resolution-limited staining foci." (PMID 25765654, 2015). "We estimated the cellular concentration of RAD51 in human tumor cells and found that the concentration in MCF7 is about 0.32 μM, a concentration at which purified RAD51 displays significant binding to dsDNA." (PMID 25765654, 2015). "However, no inactivating mutations of RAD51, a crucial HR protein, have been reported in tumours." (PMID 24811120, 2014). "We analyzed the ROC curves for all previously known potential factors, including age, tumor size, hemoglobin, along with our potential markers: BRCA1, BRCA2, RAD51, FANCD2, BLM and BRIP1." (PMID 24708616, 2014). "The levels of DNA repair enzyme mRNA expression (hOGG1, RAD51, MUYTH and MTH1) were determined in tumor specimens and compared with normal mucosa." (PMID 23389043, 2013). "Variables that were selected for multivariate analysis included XRCC3, RAD51, HER2, ER, PR, age at diagnosis, histology grade, tumor size, and axillary lymph node metastasis." (PMID 23977219, 2013). "Concurrently, tumor tissue and primary cultures displayed low transcript levels of proliferation-related genes, such as, TOP2A, ANKT, RAD51, UBE2C, CENPA, RRM2, and PLK." (PMID 15260889, 2004). "In vivo, combined treatment with anlotinib and RAD51-IN-1 significantly reduced tumor burden without notable toxicity." (PMID 41984951, 2026). "Although B02 is not tumor-specific in its uptake, previous studies have shown that non-malignant cells are less reliant on HR and thus exhibit reduced sensitivity to RAD51 inhibition under sublethal DNA damage conditions." (PMID 40824344, 2026). "In conclusion, our integrated multiomics and experimental analysis establishes a foundational framework in which RAD51 acts as a central oncogenic driver in OSCC, promoting tumour progression through regulation of cell proliferation, invasion, chemoresistance and immune evasion." (PMID 41350246, 2025). "The ESTIMATE algorithm revealed negative correlations between RAD51 expression and ImmuneScore, StromalScore and ESTIMATEScore, suggesting its potential suppressive effect on the immune landscape and tumour microenvironment in OSCC." (PMID 41350246, 2025). "Collectively, RAD51 orchestrates an immunosuppressive landscape in OSCC, characterised by broad negative correlations with immune cell infiltration (16/24 subtypes) and suppressed tumour microenvironment scores." (PMID 41350246, 2025).
tumor (continued). "Additionally, MB-3 significantly increased the tumor-killing effect of CDDP in A2780-shRAD51 and OVCAR8-shRAD51 cells transfected with the WT RAD51 vector, the effect of which was attenuated by the RAD51 K73R mutant vector." (PMID 40083924, 2025). "Moreover, the correlations among BCKDK, p‐RNF8S157, RAD51, and HRR marker p‐RPA32 were validated by IHC staining of patient samples, suggesting that high BCKDK levels in tumor regions exhibit increased DNA repair ability." (PMID 40298908, 2025). "In addition, BBIT20-treated tumours showed a reduced number of BRCA1- and RAD51- positive cells, supporting the inhibitory effect of BBIT20 on HR." (PMID 40275348, 2025). "Tumor biopsies from the patient with cPR demonstrated high baseline expression of SLFN11 and a unique pattern of pharmacodynamic responses, including increased RAD51, phosphorylated KAP1 (pKAP1), γH2AX, and cleaved caspase-3 (cCasp3)." (PMID 40439882, 2025). "The academic and commercial tests set up to define the HRD status of the tumor rely on DNA sequencing analysis, while functional tests such as the RAD51 foci assay are currently under study, but have not been validated yet and are available for patients." (PMID 38989145, 2024). "Studies have demonstrated that antiangiogenic drugs have multiple effects on homologous recombination deficiency (HRD), including reducing angiogenesis, creating hypoxia in tumor microenvironment, and downregulating BRCA1/2 and RAD51, two of the most important components in HRD." (PMID 39624625, 2024). "IHC of continuous sections obtained from the same patient's cancerous and non-cancerous tissues revealed that CPNE3, YAP1, CYR61, and RAD51 were significantly positive in the tumor tissue and negative in the non-cancerous tissue." (PMID 38493426, 2024). "Mechanistically, PARP/HDACi increased the acetylation of H3K9 and H2A.X phosphorylation and reduced the expression of RAD51 and BRAC1 on tumor cells in MDA-MB-436 and 4T1 mice, suggesting that the antitumor effect in vivo coincides with disruption of PARP and HDAC enzymatic activity." (PMID 38182579, 2024). "Despite no significant change in RNA levels, RAD51 protein is downregulated in both murine and human tumor cells after short-term in vitro drug treatment." (PMID 38849845, 2024). "Analysis of the 48 PARPi-resistant BRCA1-deficient (32 KB1P and 16 KB1PM tumors) tumors revealed that 60% (29/48) of the tumors had restored the capacity to form RAD51 foci, including one tumor with a mixed pattern (RAD51-IRIF-positive and -negative areas)." (PMID 37209095, 2023). "The availability of a sensitive, non-DNA-based, method like the RAD51-FFPE test addresses this need and fills an important gap in the diagnostic landscape as, in contrast to the RECAP test, no ex vivo irradiated fresh tumor tissue is required." (PMID 37725154, 2023). "To determine the sensitivity and specificity of the RAD51-FFPE test to identify functional HRD, we performed the RECAP test on viable, cryopreserved, matching tumor samples on the premise that the HRD status as determined by the RECAP test faithfully represented the functional HR status." (PMID 37725154, 2023). "Assaying RAD51 function, rather than HRD-associated genomics, is an attractive approach, as it measures current, not historical, HR capacity of tumor cells and is mutation-agnostic." (PMID 36805632, 2023). "Furthermore, we further stained Rad51 and p-CHK1 in tumor tissues of the CDX model, and observed the reduction of these two factors in tumors derived from SENP5 KD cells." (PMID 37684630, 2023). "However, the expression of tumor stemness markers, including CD44, CD133, Nanog, Oct4, and SOX2, was similar between OECM1 EV and OECM1 RAD51 OE cells." (PMID 37798649, 2023). "In addition, FOXM1 is an upstream regulator of various DNA damage repair genes such as XRCC1, BRCA2, RAD51, BRIP1 and NBS1, thereby enabling the tumor cells to resist the action of the genotoxic agents." (PMID 37025658, 2023).